MMP2 (matrix metallopeptidase 2)
Diseases named in the same sentence as MMP2 in open-access papers (continued):
Sharing a sentence is not in itself a finding about the gene and the disease.
tumor (continued). "The two drugs work synergistically to inhibit tumor growth and metastasis, in part by inhibiting autophagy, which in turn suppresses tumor fibrosis and down-regulates MMP-2, further inhibiting metastasis." (PMID 34522207, 2021). "The TCGA (The Cancer Genome Atlas) data also show the increased level of MMP-14 and MMP-2 in most kinds of tumor tissues." (PMID 34620867, 2021). "The effect of GQD was attributed to the inhibition of the expression and activity of matrix metalloproteinase-2 (MMP-2), which is a critical factor for tumor neovascularization and avascular expansion." (PMID 34025427, 2021). "The conjugation of DTX to the polyanionic inhibitory peptide EGGEGGEGG, the MMP-2/9-sensitive cleavable peptide (PVGLIG) and the cell-penetrating domain R9 was associated with enhanced cancer cell-specific uptake of DTX in MMP-2/9-overexpressing tumor tissues." (PMID 34575464, 2021). "In a 1,2-dimethylhydrazine-induced colon cancer rat model, treatment with piroxicam and C-PC resulted in a lower tumor expression of MMP-2 and MMP-9 compared to a control." (PMID 33498927, 2021). "Altogether, the effects in Batf3–/– mice highlight that cDC1s are negatively affected by OE of Mmp2 and, in their absence, tumor growth in response to Mmp2 OE is compromised." (PMID 34032639, 2021). "In our study, ALX1 overexpression promoted tumor progression in EC at least partly through upregulation of MMP2, MMP9, VEGF and vimentin." (PMID 34104082, 2021). "As a heterodimeric transcription factor, NF-κB is composed of p50 and p65 subunits, mediates tumor invasion and metastasis through regulating the expressions of metastasis-associated proteins such as XIAP, MMP-2, MMP-9, cyclinD1, and VEGF." (PMID 35002708, 2021). "miR-3182 down-regulation was associated with up-regulation of genes involving several vital signaling pathways in carcinogenesis and tumor metastasis, including mTOR and MMP2." (PMID 33882454, 2021). "The six genes belonged to different functional groups: antigen presentation (HLA-DPA1 and CD1C), innate immune response (TLR7), type II interferon signaling (IFNB1), tumor marker (MMP2), and proliferation marker (MKI67)." (PMID 34209514, 2021). "Oct4A is a transcription factor, suppression of which is associated with decreased expression of integrin β1, α5, and α2 subunits leading to diminished adhesion of tumor cells to collagen and fibronectin, decreased levels of MMP-2, and certain markers." (PMID 33859913, 2021). "MMP-2, which belongs to the same gelatinase family as MMP-9, is also highly associated with various tumor entities such as prostate cancer, gastrointestinal carcinomas, and cervical cancer." (PMID 34055644, 2021). "In contrast, EM046 cells, isolated from a stage IB undifferentiated tumor, displayed both MMP2 and α-smooth muscle actin expression, as well as vimentin on both protein and mRNA level." (PMID 34936030, 2021). "A phase 1 clinical trial assessing CAR T cells with a chlorotoxin tumor-targeting domain in MMP2-positive recurrent or progressive GBM is currently recruiting patients (NCT04214392)." (PMID 34884607, 2021). "The abundant matrix metalloproteinase 2 (MMP-2) in the tumour environment intercepted and cut off the short peptide chain structure grafted on APP-DOX." (PMID 34630113, 2021). "Similar to MMP-9, IR also induces upregulation of MMP-2 resulting in enhanced tumor growth and cell invasiveness." (PMID 34055644, 2021). "The degradation of the basement membrane—a prerequisite for tumor invasion—is mediated mainly by MMP-2 and -9." (PMID 35010907, 2021). "Although the specific tumor cell surface receptor for CLTX has not been identified, this study found that the CLTX CAR T cells tumor recognition was mediated by expression of membrane-bound matrix metalloproteinase-2 (MMP-2) on the tumor cells." (PMID 34421912, 2021). "To assess the role of host Tlr2 and Tlr4 in Mmp2-OE and Mmp2-KO tumor kinetics, we compared tumor growth in the Tlr2–/–Tlr4–/– DKO mice." (PMID 34032639, 2021).
tumor (continued). "Tumor cells mitigate the immune response by releasing MMP-2, MMP-9, MMP-13 and MMP-14, resulting in the inhibition of T-cell proliferation and antigen presentation." (PMID 34204372, 2021). "Nude mice xenografts, established using HCC cells, were treated with 25 mg/kgd Icariside II for 30 days and exhibited a remarkable reduction in tumor volume, weight, and the protein levels of MMP2/9 and BCL-2/Bax ratio compared to the DMSO-treated group." (PMID 33981241, 2021). "Previous works also indicated that metastatic melanoma cells secrete a large amount of TNF-α, IL-6, IL-12, IFN-γ, VEGF, eotaxin, and RANTES, triggering a cascade of effects that include the increase of MMP-2 enzymatic activity and tumor cell aggressiveness." (PMID 33466236, 2021). "This is associated with increased expression of estrogen receptors alpha and beta and MMP2, which plays a significant role in degrading collagen and facilitating tumor invasion." (PMID 34684173, 2021). "The NPs had an average diameter of 25 nm, and these crossed the BBB following i.v. injection and degraded in the brain by tumor‐derived MMP‐2." (PMID 34105297, 2021). "The MMP-2-mediated shedding of the dentrimer exposes Fl and promotes Fl-receptor-mediated tumor targeting." (PMID 34834199, 2021). "The NPs are functionalized with folate (Fl) and a polyethylene glycol (PEG) polyamidoamine (PAMAM) dendrimer containing a matrix metalloproteinase–2 (MMP-2)–cleavable peptide that guarantees NP stability in blood circulation and tumor-specific uptake." (PMID 34834199, 2021). "FL SPARC stimulates migration and invasion of TNBC cells 63, and promotes MMP-2 activation in TNBC cells, thereby contributing to the proteolytic cascades associated with tumor invasion." (PMID 33995652, 2021). "Multiple proteins such as MMP-2/7 play essential roles in the migration and invasion of tumour cells through regulation of degradation of extracellular matrix proteins." (PMID 34315493, 2021). "MMP-2-catalyzes cleavage of fibronectin (FN) and vitronectin (VN) and facilitates tumor cell–mesothelial cell adhesion that initiates metastases." (PMID 33810259, 2021). "A higher level of E-cadherin and lower levels of MMP-2 and N-cadherin were examined in tumor tissues in DIE-treated mice." (PMID 34639167, 2021). "Additional correlative studies using CM harvested from a variety of PDAC tumor cell lines with varying MMP2 levels were also performed." (PMID 33740019, 2021). "MMP-2 and MMP-9 mRNA expressions were enhanced with the increase of the tumor clinical Stages (MMP-2: F = 4.003, p = 0.026, MMP-9: F = 5.501, p = 0.008)." (PMID 31882379, 2021). "In this study, gold nanoclusters were decorated with PEG to increase their stability and biocompatibility, they were also coated with MMP2 polypeptides to specifically target the tumor tissue." (PMID 34834387, 2021). "The tumours expressed lower levels of lamin B1 (a Dp71-binding partner), matrix metalloproteinase 2 (MMP-2) and B cell lymphoma 2 (Bcl-2), which the authors linked to the reduced malignancy in this model." (PMID 33188621, 2021). "Curcumin has been shown to significantly reduce tumor volume, and activity of MMP-2 and MMP-9 at the tumor-bearing site." (PMID 33578780, 2021). "MMP-2 is secreted by tumor cells and interstitial cells in the form of a zymogen and can specifically degrade collagen IV when it is hydrolyzed and activated." (PMID 31882379, 2021). "Immunohistochemistry analysis showed a significant increase in E-Cadherin, and reduction in MMP-2 and Vimentin level in tumor samples obtained from animals simultaneously administered Iminodibenzyl (20 mg/kg) and DGLA (5 mg) (P < 0.001)." (PMID 34535685, 2021). "For the further understanding its mechanism, the position of MMP2 in tumor tissues need to be determined." (PMID 34976953, 2021).
tumor (continued). "The diagnostic sensitivity of TIMP-1 was higher (61%) than that of the serum levels of other biomarkers (MMP-9—55%; TIMP-2—59%, MMP-2—46%) as well as the classical tumor markers (CEA and CA 19-9), and increased in combined use with CEA." (PMID 34071492, 2021). "The results indicated that the SCC-PDSX promotes MMP2-positive BMDCs recruitment to the invasive front line of the tumor." (PMID 35008304, 2021). "With the downregulation of circ_0000620, we found that E-cad protein level was increased but the levels of MMP2 and N-cad were reduced in tumor tissues." (PMID 34972532, 2021). "The acidic tumor microenvironment can induce the expression of MMPs such as MMP-2 and MMP-9 and enhance the invasion and metastatic ability of tumor cells." (PMID 34976805, 2021). "In OSCC, the expression of MMP9 and MMP2 in tumor and stromal cells defined the invasiveness of oral cancer." (PMID 35008304, 2021). "On the other hand, the expression of metastatic tumor indicators, CD44v6, MMP-2, and MMP-9 decreased in A549 cells exposed to VPA." (PMID 34400947, 2021). "In acidic tumor tissues, the PEG outer chains were shed from nanodrugs to promote the cellular uptake by tumor cells, and the overexpressed intratumoral MMP-2 cleaved the peptide linkers to trigger the release of anti-PD-L1." (PMID 34660560, 2021). "Three variables were negatively associated with this Dim and reflected tissue remodelling (IAT MMP2 (r2 = −0.6283, p = 0.0287), tumour MMP2 and MMP3 (r2 = 60.6606, p = 0.0194; r2 = −0.6790, p = 0.0152 respectively))." (PMID 32472095, 2020). "The nanoparticles accumulated in the tumor location through the EPR effect, followed by the breakage of the crown in response to the over-expressed MMP-2 in the tumor microenvironment." (PMID 32850662, 2020). "To further elucidate the relationship between Porf-2 and the MMPs with regard to the inhibition of tumor cell migration, we designed a rescue assay by overexpression of MMP-2." (PMID 32676454, 2020). "Functionally, EFEMP1 inhibits migration of tumor cells by regulating MMP2 and MMP9 via ERK1/2 activity." (PMID 32555395, 2020). "The highest values of SE were obtained for the combination of MMP-2 with the commonly accepted tumor markers in all stages of cancer." (PMID 30820752, 2020). "As a result, it was expected that a high level of TIMP-2—by inhibiting MMP-2 and its procancerous activity—will result in inhibition of cell growth and tumor spread, improving patient prognosis." (PMID 32751899, 2020). "In a tumor microenvironment that overexpressed MMP-2 and enriched GSH, the supramolecular hydrogel was degraded into fragments and then into monomers, leading to the drug release for effective chemotherapy." (PMID 34123123, 2020). "As evident from the results of the IHC analysis, the proportions of Ki‐67‐positive and MMP2‐positive cells were significantly lower in the tumour sections of the BA‐treated group than those in the sections of the control group." (PMID 32283563, 2020). "Elastokines containing the GxxPG motif such as VGVAPG (VG-6) promote tumor progression by stimulating cell invasion through the activation of proteolytic cascades, especially MMP-2 and uPA." (PMID 33396696, 2020). "Previous studies have evidenced that MMPs, particularly MMP-2 and -9, play important roles in cancer metastasis, contributing to angiogenesis, intravasation of tumor cells, and cell migration and invasion." (PMID 32492880, 2020). "Studies revealed that anti-tumor drugs inhibited the M2-associated genes, such as CD206, Arginase 1, CD204 and MMP2 in AOM/DSS mouse models." (PMID 33201893, 2020). "The reduced production as well as the activation of c-JUN protein induced by LCL-PLP in the combined therapy has the potential to decrease the metastatic potential of the tumor cells via the inhibition of MMP-2 activation." (PMID 32340166, 2020).
tumor (continued). "Our results demonstrated that the concomitant administration of LCL-PLP and LCL-DOX induced a strong inhibition of tumor growth, primarily by inhibiting TAMs-mediated angiogenesis as well as the tumor production of MMP-2 and AP-1." (PMID 32340166, 2020). "Because of the overexpression of MMP‐2 protein in the tumor environment, such prodrug nanoparticles preferentially release DOX at the tumor site to induce apoptosis and an antitumor immune response." (PMID 33304763, 2020). "The results showed that LS276-THP was suitable for the detection of tumor-related MMP-2 and MMP-9 in vivo." (PMID 32259133, 2020). "Upregulation of the MMP-2 in the fibroblasts neighboring the tumor was observed in about 50% of the NSCLC patients, enabling malignant transformation by ECM degradation and the creation of a suitable microenvironment for vessel growth." (PMID 33126605, 2020). "There are at least 23 MMPs and four types of TIMPs expressed in humans, but MMP-2, MMP-9, MMP-14, TIMP-1, and TIMP-2 are often associated with the tumor invasion process." (PMID 32669083, 2020). "In comparison to a wild-type fiber adenovirus, AdTATMMP demonstrated increased infection of tumor cells as well as patient-derived CAFs that highly expressed MMP2 and MMP9." (PMID 33167307, 2020). "Further, in the presence of the cell-scale MMP-2 source induced by the macro-dynamics, a cross-interface diffusion of MMP-2 occurs at the invasive edge of the tumour." (PMID 32458057, 2020). "We have also demonstrated that an elastin nonapeptide of consensus sequence xGxPGxGxG, AGVPGLGVG (AG-9), favors the migration and invasion of tumor cells through MMP-2 and uPA increases." (PMID 33396696, 2020). "Myoepithelial cells can act on tumor cells and on fibroblasts to reduce MMP-2, MMP-9, and MT1-MMP gene expression, decreasing cancer cells invasive capacities." (PMID 32984031, 2020). "Among these genes, four genes (TIMP1, MAPK13, MAPKAPK2 and MAPKAPK3) are known to regulate cell proliferation, and MMP2 and MMP9 control tumour-associated tissue remodelling; PIK3CD is involved in the immune response, and AKT2 regulates tumourigenesis." (PMID 32999349, 2020). "The presence of MMP-2 in the stroma of the tumor was a protective factor while the presence of MMP-2 in the epithelium indicated an adverse prognosis." (PMID 32718331, 2020). "This work shows that the collective invasion of cancer cells is tuned by a balance between the expression levels of FAK and MMP-2 in cancer cells as well as on the presence of CAFs in the tumor microenvironment." (PMID 33321813, 2020). "Tumor progression, in particular, tumor metastasis can also be supported by MMP2, which facilitates tissue penetration by cancer cells." (PMID 32560387, 2020). "The combined use of M-CSF, MMP-2 or TIMP-2 with the commonly accepted tumor markers (antigen SCC and CA 125) resulted in an increase in the sensitivity range in the total CC group." (PMID 30820752, 2020). "MMP-2 was found in tumor homogenates by ELISA and its expression was localized to the extracellular matrix." (PMID 32848608, 2020). "The results showed increased concentration of MMP-2 (among others) in tumor tissue compared with tumor-free tissue." (PMID 32751899, 2020). "Staining of the tumour sections revealed that the expression level of MMP2 and Ki‐67 was higher in the sh‐NC group compared with the sh‐LINC01128 group." (PMID 33108067, 2020). "Up-regulation of MMP2 has been found in many tumors, and its increase promotes the proliferation, motility and metastasis of malignant tumor cells." (PMID 33115469, 2020). "Here, we found that RGS4 silencing decreased the expression, secretion and activity of MMP2, a key MMP associated with tumor dissemination and invasiveness." (PMID 32392739, 2020). "Similar to data obtained in this study, upregulated expression of TLR9 in HNSCC as well OSCC was found to promote tumor cell invasion, proliferation as well as migration by enhancing MMP-2 expression." (PMID 32961854, 2020).
tumor (continued). "β-cryptoxanthin inhibited the migration of AGS and SGC-7901 gastric cancer cells, as demonstrated by decreased protein levels of MMP-2 and -9 and suppressed tumor growth in murine AGS xenografts." (PMID 33321708, 2020). "The inhibition of MMP2/9 by SB-3CT significantly reduced the tumor burden and improved survival time via the promotion of anti-tumor immunity, potentially through reducing PD-L1 expression." (PMID 32988398, 2020). "MMP2 is involved in the degradation of tumor basement membrane and extracellular matrix, and the complex formed by MMP2 and MMP14 promotes the formation of blood vessels." (PMID 33098235, 2020). "MMP9 and MMP2 are important members of the MMPs family, secreted by neutrophils, macrophages and tumor cells, which participate in the depletion of ECM and play an important role in the vascularization of malignant tumors and the infiltration of tumor cells." (PMID 33292262, 2020). "It is known that higher MMP2 and MMP9 and lower laminin and fibronectin are associated with migration and invasion of tumor cells." (PMID 33519431, 2020). "A previous study stated that both mRNA and protein levels of MMP2 in tumor tissues were decreased through the PD-L1 blockade." (PMID 31936263, 2020). "In the present study, the combined use of M-CSF, MMP-2 or TIMP-2 with the commonly accepted tumor markers resulted in an increase in SE values." (PMID 30820752, 2020). "This type of collagen is released by a primary tumor in response to the hypoxic conditions in the tumor environment, where BMDCs degrade collagen type IV through the expression of MMP-2, which contributes to invasion and metastatic growth." (PMID 33419373, 2020). "A previous study has indicated that the dynamic balance between TIMP-2 and MMP-2 can affect tumor invasion and metastasis." (PMID 33027062, 2020). "For instance, the overexpression of miR-874 targeting MMP-2 decreases tumor cells’ invasiveness in vitro as well as decreases tumor growth in vivo." (PMID 33321819, 2020). "We found MMP-2 blocked the effect of Porf-2 on tumor cell migration, demonstrating that Porf-2 mediates tumor cell migration through the MMP signaling pathway." (PMID 32676454, 2020). "MMP2 plays an important role in the invasion and metastasis of GC and can promote tumor invasion and metastasis by degrading the extracellular matrix, promoting neovascularization, and regulating cell adhesion." (PMID 32020871, 2020). "An interesting study showed that the downregulation of Notch 4 disrupted VM network formation and inhibited the invasion and migration of tumor cells by inhibiting the activation of MMP-2 and MMP-9 in HCC." (PMID 32169087, 2020). "In fact, due to the breakdown of basement membrane collagen IV, MMP-2 and MMP-9 overexpression confers a poor prognosis for EC patients and is associated with late tumor stage, as well as with local invasion and presence of metastasis." (PMID 32079295, 2020). "Upregulation of pro-invasive enzymes such as matrix metalloproteinase-2 (MMP2) contributes to the invasion of tumor cells." (PMID 33375117, 2020). "They showed that NAA10 interacts with matrix metalloproteinase-2 (MMP-2) via its acetyltransferase domain and in turn promotes the stabilization of MMP-2 protein, leading to the increases in cell invasion and tumor metastasis." (PMID 33126484, 2020). "Several MMPs were found to be expressed by the cancer cells (e.g., MMP-7); however, others were synthesized by the tumor stromal cells (e.g., MMP-2, MMP-9)." (PMID 33287452, 2020). "When a tumor first becomes vascularized (angiogenic switch), MMP-2 and MMP-9 have been shown to be critical for tumor angiogenesis." (PMID 33096744, 2020). "CCR7 has also been found to induce EMT in PDAC and lung cancer (LC), promote MMP-2 and -9 expression in bladder cancer, and facilitate tumor cell dissemination, migration, and eventually metastasis formation." (PMID 31991604, 2020).